ADAMTSL5 (ADAMTS like 5)
Description:
May play a role in modulation of fibrillin microfibrils in the extracellular matrix (ECM).
Synonyms: THSD6
Gene: Protein-coding gene on chromosome 19 (1,505,022 to 1,513,604, reverse strand). Ensembl gene ENSG00000185761.
Subcellular location: Secreted; Secreted, extracellular space, extracellular matrix
Subcellular location (Human Protein Atlas): Golgi apparatus; Predicted to be secreted
Pathways (Reactome):
Disease: Defective B3GALTL causes PpS
Metabolism of proteins: O-glycosylation of TSR domain-containing proteins
Genetic constraint (gnomAD): Loss-of-function variants: 59 observed, 52.08 expected, observed/expected ratio (o/e) 1.13, 90% interval 0.92 to 1.41. The upper end of that interval is the gene's LOEUF score, 1.41, which puts it in group 5 of 6, group 1 being the genes least tolerant of losing a copy. Missense variants: 770 observed, 613.41 expected, observed/expected ratio (o/e) 1.26, 90% interval 1.18 to 1.33. Synonymous variants: 285 observed, 245.27 expected, observed/expected ratio (o/e) 1.16, 90% interval 1.05 to 1.28.
Homologues: Orthologues: chimpanzee ADAMTSL5 (98% identical), macaque ADAMTSL5 (94% identical), pig ADAMTSL5 (82% identical), mouse Adamtsl5 (80% identical), rat Adamtsl5 (80% identical), guinea pig ADAMTSL5 (79% identical), dog ADAMTSL5 (76% identical), tropical clawed frog XB995277 (40% identical), zebrafish adamtsl5 (37% identical). Paralogues in human: ADAMTSL4 (33% identical), THSD4 (31% identical), PAPLN (30% identical), ADAMTS16 (29% identical), ADAMTS7 (28% identical), ADAMTS12 (28% identical), ADAMTS18 (28% identical), ADAMTSL2 (28% identical), ADAMTS6 (27% identical), ADAMTS9 (27% identical), ADAMTS19 (26% identical), ADAMTS15 (25% identical), and 13 more.
Diseases named in the same sentence as ADAMTSL5 in open-access papers:
ADAMTSL5 is named in the same sentence as 17 diseases in open-access papers, as found by Europe PMC text mining. Sharing a sentence is not in itself a finding about the gene and the disease. The quoted sentences say what the papers report.
psoriasis (33 papers, 2016 to 2025). An autoimmune condition characterized by red, well-delineated plaques with silvery scales that are usually on the extensor surfaces and scalp. "Future research should focus on exploring immune tolerance induction as a novel treatment approach, particularly through antigen-specific immunotherapy targeting psoriasis-associated autoantigens such as K17 and ADAMTSL5." (PMID 41009795, 2025). "This prokaryotic expression system, yielding ample quantities, coupled with its mature technology, establishes a framework for subsequent ADAMTSL5 functional studies and the auxiliary diagnostic utility in psoriasis." (PMID 39670545, 2024). "The expression of the psoriasis autoantigen ADAMTSL5 and the genetic susceptibility to psoriasis of the three patients were also studied." (PMID 38495872, 2024). "ADAMTS-like protein 5 (ADAMTSL5), a melanocyte protein, was identified as an autoantigen in psoriasis presented by HLA-C*06:02, the main psoriasis risk gene." (PMID 38642273, 2024). "The ADAMTS family member, ADAMTSL5, has already been associated with psoriasis and its musculoskeletal manifestations, showing an association between psoriatic arthritis and ADAMTSL5 antibodies." (PMID 36677041, 2023). "A Disintegrin-like and Metalloprotease domain containing Thrombospondin type 1 motif-like 5 (ADAMTSL5) is a melanocyte-derived protein that has recently been implicated as an activating antigen for IL-17-producing T cells in psoriasis." (PMID 27857980, 2016). "HLA-C*06, a human leukocyte antigen (HLA) allele, triggers psoriasis by inducing an autoimmune response against melanocytes through presentation of the “a disintegrin and metalloproteinase with thrombospondin motifs-like 5” (ADAMTSL5) autoantigen." (PMID 41009795, 2025). "Overall, numerous studies have highlighted the adjacent association between ADAMTSL5 and psoriasis." (PMID 39670545, 2024). "In line with the homeostatic importance of Tregs in psoriatic disease, we observed a relation of Foxp3 instability with loss of immune tolerance in psoriatic disease: presence of ADAMTSL5 antibodies in psoriasis and PsA reflected the balance between Foxpint and Foxp3hi Tregs." (PMID 36450783, 2022). "Similarly, psoriasis patients with HLA-C∗06:02 susceptibility locus can also present ADAMTSL5 peptide as an autoantigen." (PMID 31130981, 2019). "A disintegrin and metalloprotease domain containing thrombospondin type 1 motif‐like 5 (ADAMTSL5), a protein linked to psoriasis, was obtained by prokaryotic expression and purification for potential utilization as a new auxiliary diagnostic marker for psoriasis." (PMID 39670545, 2024). "In addition, cytotoxic CD8+ T (Tc) cells can also express IL-17A (Tc17) upon recognition of the self-antigen ADAMTSL5 via HLA-C*06:02 which is the strongest psoriasis susceptibility allele in psoriasis patients revealing their pivotal pathogenic role in psoriasis." (PMID 37594540, 2023). "Significantly increased frequencies of ADAMTSL5-specific CD8+ T cells and high ADAMTSL5 serum autoantibody titers in the blood of psoriasis patients further emphasize the role of ADAMTSL5 as a psoriasis autoantigen." (PMID 41440022, 2025). "This is reflected in significantly elevated frequencies of ADAMTSL5-specific CD8+ T cells circulating in the blood of psoriasis patients." (PMID 41440022, 2025). "Significantly increased blood levels of ADAMTSL5-specific CD8+ T-cells and ADAMTSL5 autoantibodies in psoriasis patients substantiate the role of ADAMTSL5 as a psoriatic autoantigen." (PMID 40243413, 2025). "Our study showed that adaptive immunity predominates over innate immunity in anti-PD-1-induced psoriasis lesions, consistently with the local ADAMTSL5 overexpression." (PMID 38495872, 2024). "The particular immunogenicity of ADAMTSL5 and wheat peptides for psoriasis patients is highlighted by the coincidence of significantly increased stimulation-induced [3H]-thymidine incorporation and CD137 expression on CD8+ T cells." (PMID 38524140, 2024).
psoriasis (continued). "We next evaluated the expression of the melanocyte- and keratinocyte-derived autoantigen ADAMTSL5, whose expression has been found to be dysregulated in psoriasis and in many cancer types, including melanoma." (PMID 38495872, 2024). "Among them, CD8+ T cells were found in the epidermis of skin lesions and in close contact with keratinocytes, consistently with the local overexpression and exposure of ADAMTSL5 psoriasis autoantigen." (PMID 38495872, 2024). "The independent sample t‐test analysis of luminescence value data performed using GraphPad Prism software indicated that the anti‐ADAMTSL5 luminescence level in the serum of psoriasis patients was higher than that in healthy individuals." (PMID 39670545, 2024). "In psoriasis patients, specific immune responses induced by ADAMTSL5 autoantigen are represented primarily by IL-17A-producing CD8+ T cells and directed against melanocytes and surrounding keratinocytes." (PMID 38495872, 2024). "Here, we also show that ADAMTSL5 antigen was strongly expressed in psoriasis lesions of the three oncological patients, at similar expression levels and localization of chronic plaque-type psoriasis." (PMID 38495872, 2024). "In recent years, ADAMTSL5, a newly discovered protein, has emerged as an activated antigen of psoriasis." (PMID 39670545, 2024). "Among them, the haplotype 2 (rs26653) can control the autoimmune response against melanocytes in psoriasis by generating ADAMTSL5 antigen epitopes." (PMID 38495872, 2024). "The expression of ADAMTSL5 in this investigation offers essential material for in‐depth exploration of its involvement in elucidating the pathogenesis of psoriasis and other diseases." (PMID 39670545, 2024). "Purified ADAMTSL5, obtained in conjunction with magnetic beads, was directly employed in both psoriasis patients and healthy individuals." (PMID 39670545, 2024). "Nevertheless, this experiment offers technical support for the production of ADAMTSL5 and contributes scientific value to understanding the relationship between ADAMTSL5 and psoriasis." (PMID 39670545, 2024). "Later, we discovered that the antimicrobial peptide (AMP) cathelicidin LL37 is an autoantigen in psoriasis, and another study found that ADAMTSL5 is also an autoantigen in psoriasis." (PMID 36901778, 2023). "In psoriasis, ADAMTSL5 is present in human leukocyte antigen (HLA)-restricted melanocytes that activate interleukin (IL) 17-producing T cells." (PMID 35587154, 2022). "ADAMTSL5 autoantibodies discriminated between psoriasis and PsA diagnosis with an AUROC of 0.67 (95%CI 0.543–0.787), P = 0.012)." (PMID 36450783, 2022). "Two antigens expressed in the psoriatic skin, ADAMTSL5 and a cathelicidin, LL-37, towards which an autoimmune activity was shown to be directed in psoriasis, were identified as autoantigens in PsA as well." (PMID 33581710, 2021). "A fascinating case study with a unique methodology identified ADAMTS-like 5 (ADAMTSL5) as an HLA-C*06:02-presented melanocytic autoantigen to the lesion-infiltrating autoreactive CD8+ T cells in psoriasis." (PMID 33581710, 2021). "IgG autoantibodies against ADAMTSL5 and LL-37 were shown to be present in PsA even with higher concentrations than in psoriasis-only patient sera significant enough to differentiate PsA and psoriasis." (PMID 33581710, 2021). "An elegant work by Arawaka and co-workers demonstrated for the first time that ADAMTSL5 is a melanocyte autoantigen in Psoriasis." (PMID 33348540, 2020). "The ADAMTSL5 expression pattern mirrors the pattern of T cell infiltration and DC aggregation in the superficial dermis in psoriasis, which is similar to LL37." (PMID 33050592, 2020). "ADAMTSL5 antibody made in chicken showed a strong expression on perivascular dermal cells and dendritic cells, but weaker staining on keratinocytes in psoriasis lesional skin." (PMID 27857980, 2016).
psoriasis (continued). "A recent study by Prinz’s group implicates ADAMTSL5 as an auto antigen in psoriasis, which has been categorized as an autoimmune disease." (PMID 27857980, 2016). "Overall, the pattern of ADAMTSL5 expression is very similar to the infiltrating pattern of T-cells and dendritic cells in psoriasis lesions." (PMID 27857980, 2016). "The pattern of ADAMTSL5 expression is thus similar to the infiltrating pattern of T-cells and dendritic cells in psoriasis." (PMID 27857980, 2016). "We examined the expression of ADAMTSL5 in psoriasis skin and confirmed the staining of scattered basal cells with melanocyte morphology, in agreement with the observations of Prinz’s group." (PMID 27857980, 2016). "Melanocytes have also been recently proposed as target cells of the HLA-C*06:02-restricted autoimmune response in psoriasis via the melanocyte autoantigen ADAMTSL5, which could provide a skin-specific target for autoimmune attack." (PMID 40021644, 2025). "Additionally, a notable disparity was observed between the levels of anti‐ADAMTSL5 in the serum of healthy individuals and those with psoriasis *** p < 0.001." (PMID 39670545, 2024). "There is the possibility that anti-PD-1-induced immune responses specific for ADAMTSL5 could be responsible for both anti-PD-1-induced psoriasis, and for an effective immune response against melanoma cells." (PMID 38495872, 2024). "It explores the potential of ADAMTSL5 as a new psoriasis marker, which may serve as a reference for differential diagnosis." (PMID 39670545, 2024). "Moreover, significantly more CD8+ T cells were observed to recognize both ADAMTSL5 and wheat peptides in psoriasis patients than in healthy controls." (PMID 38524140, 2024). "Furthermore, it employed economical and simple technical methods and effectively combined ADAMTSL5 with magnetic bead particles, providing designs and techniques for further studies on diagnosing psoriasis and related disorders." (PMID 39670545, 2024). "The experimental findings presented here may contribute to the utilization of ADAMTSL5 as a marker for diagnosing psoriasis, offering novel insights and experimental avenues for further investigation." (PMID 39670545, 2024). "The high frequency of circulating ADAMTSL5-specific T cells detected in psoriasis patients may reflect the fact that the large number of pathogenic T cells infiltrating psoriatic skin lesions may require a continuous T cell supply from the circulation." (PMID 38524140, 2024). "Importantly, in patient 2, ADAMTSL5 expression was not only found in psoriasis skin lesions but also in most melanoma cells of the primary tumor and in perilesional areas, specifically in melanocytes undergoing transformation." (PMID 38495872, 2024). "Indeed, some studies suggested antigenic functions of structural proteins, and complexes of self-DNA with cathelicidin (LL37) or melanocytic ADAMTSL5 have been proposed more recently as actual auto-antigens in some cases of psoriasis." (PMID 31402919, 2019). "In psoriasis patients, their melanocytes were shown to express increased levels of ADAMTSL5." (PMID 31130981, 2019). "Amino acids at anchor residues 2 and 9 of peptide antigens and ADAMTS-like protein 5 (ADAMTSL5) presented by psoriasis-associated human leukocyte antigen (HLA) molecules." (PMID 29760713, 2018). "The recent discovery of ADAMTSL5 as a potential autoantigen in psoriasis is a key finding." (PMID 27158469, 2016). "Importantly, the disintegrin and metalloprotease domain containing thrombospondin type 1 motif-like 5 (ADAMTSL5) psoriasis autoantigen was significantly upregulated in psoriasis lesions of anti-PD-1-treated patients, at levels comparable with chronic plaque-type psoriasis." (PMID 38495872, 2024). "We identified peptides from S. agalactiae, Clostridium sp., and F. plautii of the bacterial phylum Firmicutes, which activated the ADAMTSL5-specific Vα3S1/Vβ13S1 TCR and stimulated CD8+ T cells from psoriasis patients." (PMID 38524140, 2024).
psoriasis (continued). "The anti‐ADAMTSL5 levels ranged from 22,886 to 294,136 RLU, with an average of 129,000 ± 56,341 RLU in psoriasis patients." (PMID 39670545, 2024). "When PBMC were examined, the ADAMTSL5- and wheat-peptide loaded HLA-C*06:02 tetramers stained significantly more CD8+ T cells of HLA-C*06:02+ psoriasis patients than of HLA-C*06:02+ healthy subjects." (PMID 38524140, 2024). "We observed higher anti-ADAMTSL5 IgG in PsA serum (575 μg/mL (IQR 321–1523)), as compared to HC serum (205 μg/mL (IQR 28–833), P = 0.004), psoriasis serum (319 μg/mL (IQR 103–645), P = 0.012) and PsA synovial fluid (138 μg/mL (IQR 77–348), P = < 0.0001)." (PMID 36450783, 2022). "The expression of ADAMTSL5 and LL37 with DCs, neutrophils, macrophages, and T cells in psoriasis significantly decreases after treatment of IL17 or TNFα blocker." (PMID 33050592, 2020). "As this experiment aimed solely to investigate the relationship between ADAMTSL5 and psoriasis and to evaluate the potential of ADAMTSL5 as a novel psoriasis marker, reactive T cells were not assessed." (PMID 39670545, 2024). "Blood lymphocytes of more than two-thirds of psoriasis patients but not healthy controls responded to ADAMTSL5 stimulation by production of the psoriasis key cytokines, IL-17 or IFN-γ." (PMID 29760713, 2018). "If the immune reaction followed melanocyte expression of ADAMTSL5, we would expect T-cells to be more junctional rather than the epidermal and dermal patterns in psoriasis." (PMID 27857980, 2016). "Our group studied the cutaneous expression of ADAMTSL5 by performing immunohistochemistry staining on lesional and nonlesional skin biopsies from psoriasis patients using three different commercially available ADAMTSL5 antibodies." (PMID 27857980, 2016). "Immunohistochemistry staining of ADAMTSL5 was done on non-lesional and lesional psoriasis tissue using 3 different antibodies." (PMID 27857980, 2016). "To further investigate the cutaneous expression of ADAMTSL5, we performed immunohistochemistry staining on lesional and nonlesional skin biopsies from psoriasis patients using three different commercially available antibodies." (PMID 27857980, 2016). "On the other hand, extracellular deposition of ADAMTSL5, as observed in development, could also be responsible for stimulating antigen specific CD4+ T-cells (Th17 T-cells) that are also seen in psoriasis." (PMID 27857980, 2016). "ADAMTSL5 expression pattern observed in immune-related psoriasis induced by anti-PD-1 was similar to that observed in plaque-type psoriasis, even though ADAMTSL5 antigen was not always detectable in all psoriasis specimens (3 of 6 psoriasis patients were ADAMTSL5+)." (PMID 38495872, 2024). "None of the three paradoxical psoriasis to anti-TNF-α showed ADAMTSL5 positivity." (PMID 38495872, 2024). "In addition, ADAMTSL5 was not expressed in psoriasis reactions to anti-TNF-α, in line with previous findings showing an overactivation of innate immunity, and not adaptive responses, in these conditions." (PMID 38495872, 2024). "Interestingly, SLE but not atopic dermatitis controls were reported to have anti-ADAMTSL5 and anti-LL-37 IgG serum levels similar to those of psoriasis patients." (PMID 33581710, 2021). "Recent findings also showed that ADAMTSL5 can be overexpressed in keratinocytes, thus melanocytes may not be the only autoimmune targets in psoriasis." (PMID 31130981, 2019). "Moreover, peripheral lymphocytes of the majority of psoriasis patients but not individuals without psoriasis responded to ADAMTSL5 with production of IL-17 or IFNγ." (PMID 31402919, 2019). "A synthetic ADAMTSL5 peptide increases the frequency of CD8 T cells expressing IL17A and IFNɤ among the peripheral blood mononuclear cells in psoriasis patients, but the same effect is not found in healthy individuals." (PMID 33050592, 2020).
psoriasis (continued). "To show the characteristic staining pattern and distribution of ADAMTSL5 in psoriasis, we performed immunohistochemistry staining of ADAMTSL5, T-cells (CD3) and dendritic cells (CD11c) on lesional and non-lesional tissue from psoriasis patients." (PMID 27857980, 2016).
acute lymphoblastic leukemia (2 papers, 2020 to 2021). Leukemia with an acute onset, characterized by the presence of lymphoblasts in the bone marrow and the peripheral blood. "Hypermethylation of the ADAMTSL5 gene is associated with chemoresistance to acute lymphoblastic leukemia in humans." (PMID 33240310, 2020). "ADAMTSL5 was proposed as a putative epigenetic marker for therapeutic resistance in acute lymphoblastic leukemia." (PMID 33450964, 2021).
Autoimmunity (2 papers, 2021). The occurrence of an immune reaction against the organism's own cells or tissues. "Remarkably, HLA-Cw*06 was found to mediate autoimmunity against melanocytes through the ability of its protein product to present ADAMTS-like protein 5 (ADAMTSL5)." (PMID 33921427, 2021). "Entheseal and synovial cellular infiltrate with oligoclonal CD8+ T cells and occasional germinal centers, loss of regulatory T cell function, and specific autoantibodies such as anti-PsA peptide, anti-LL-37, and anti-ADAMTSL5 are the immunopathological findings suggestive of autoimmunity." (PMID 33581710, 2021).